CGAS (cyclic GMP-AMP synthase)
Diseases named in the same sentence as CGAS in open-access papers (continued):
Sharing a sentence is not in itself a finding about the gene and the disease.
tumor (continued). "Because radiotherapy can induce anti-tumor T cell responses by inducing type I IFN production in a cGAS-STING-dependent manner, cancer cells can develop resistance to radiotherapy through a loss of cGAS-STING signaling." (PMID 32774773, 2020). "Chronic cisplatin treatment (11.8 μM) promoted intratumoral T-cell accumulation and advanced tumor immunogenicity through the cGAS-STING pathway in an epithelial ovarian cancer mouse model." (PMID 32854711, 2020). "The objective of this review was to highlight how radiation-induced DNA damage leads to activation of innate immune signaling and subsequent CD8+ T cell-mediated tumor destruction through nucleic acid sensing mechanisms involving the cGAS–STING pathway." (PMID 33238631, 2020). "Based on the anti-tumor role of cGAS/STING pathway, people began to design STING agonists and cyclic dinucleotide derivatives for tumor treatment." (PMID 35006429, 2020). "Others have shown that cGAS knockdown leads to reduced DNA damage, inhibited tumor growth, and inhibited malignant cell transformation, whereas cGAS overexpression enhances the malignant potential of tumor cells in vitro and in vivo." (PMID 32774773, 2020). "cGAS-STING signaling was also revealed able to cooperate with the autophagy-ER stress responses to promote tumor progression." (PMID 32571374, 2020). "Antitumor immunity depends on the activation of the cGAS-STING pathway, as STING-deficient mice fail to stimulate tumor-infiltrating dendritic cells (DCs) to activate CD8+ T cells." (PMID 32839553, 2020). "The importance of cGAS-STING signalling in cancer is supported by preclinical models of tumours with lost or reduced STING expression." (PMID 33081170, 2020). "Antineoplastic role of cGAS has been found in multiple mouse tumor models, including colon, brain, skin, pancreatic, liver, breast, and B cell malignancies." (PMID 35006429, 2020). "Some evidence suggest that tumor cells are phagocytosed by DCs or TAMs; then, tumor DNA (nuclear or mtDNA) subsequently enter the cytoplasm from the phagosomes to activate the cGAS–STING axis." (PMID 33520994, 2020). "Radiotherapy to a tumor releases tumor-associated antigens (TAAs) and damaged DNA that can stimulate the production of type-I interferon (IFN-I) via the cyclic GMP–AMP synthase (cGAS)/stimulator of interferon genes (STING) pathway in tumor cells." (PMID 32230938, 2020). "Recent studies of the cGAS-STING pathway in anti-tumor immunity have demonstrated that cGAMP can be released into the extracellular space where its lifespan is regulated by ENPP1, a cell surface phosphodiesterase that hydrolyzes cGAMP to AMP and GMP30." (PMID 32404939, 2020). "Phagocytosed tumor derived mtDNA was also recognized by cGAS in the DC cytosol, contributing to type I IFN production and antitumor adaptive immunity." (PMID 32000794, 2020). "The endogenous cGAS production 2′,3′-cGAMP showed reduced tumor size and prolonged survival in mice bearing colon adenocarcinoma CT26 tumors." (PMID 32571374, 2020). "Because each drug targets a different part of the cancer, it is possible that cGAS-STING agonists can maximize the downstream anti-tumor response while reducing the required dose of the conventional chemotherapy drug(s), and the potential side effects." (PMID 32774773, 2020). "The sensing of tumor-derived dsDNA by cytosolic DNA sensor cyclic GMP-AMP synthase (cGAS) plays a major role in the activation of the stimulator of interferon (IFN) genes (STING) signaling pathway." (PMID 32526888, 2020). "These cancer cells transfer cGAMP—produced by cGAS in response to tumor cytosolic DNA—to astrocytes by establishing gap junctions, thereby activating STING and inducing type I IFN and TNFα expression." (PMID 32774773, 2020). "Other sources, such as apoptotic cell-derived DNA, exosomal DNA (ExoDNA), and transposable elements, have also been demonstrated to evoke cGAS–STING activation in tumor cells." (PMID 32854711, 2020).
tumor (continued). "The cGAS-STING signaling pathway is characterized as the representative production of type I IFNs to elicit anti-tumor immunity." (PMID 32887628, 2020). "The process is also independent of TLRs, AIM2, DAI, RNA polymerase III, or high mobility group box (HMGB) proteins, suggesting the primacy of the cGAS-STING mechanism in mediating the anti-tumor immune response." (PMID 32774773, 2020). "In recognition of tumor viruses, cGAS‐mediated innate immune responses are confounded by proteins from countless viruses." (PMID 32195086, 2020). "The role of cGAMP stimulating cGAS-cGAMP-STING-IRF3 pathway to inhibit tumor growth was well-established." (PMID 32596152, 2020). "The inflammatory pathway mediated by cGAS-STING is capable of potent anti-tumor responses but can also tip the system into a state of inflammation." (PMID 32774773, 2020). "The ability of transformed cells to inactivate this pathway is supposed to create a selective advantage, as cGAS-STING signalling is suppressed in several tumours." (PMID 32283785, 2020). "They further demonstrated that knockdown of cGAS impedes DNA damage and restrains tumor development both in vitro and in vivo." (PMID 32195086, 2020). "For example, blockade of CD47 promotes uptake of tumor cells by SIRPα+ cDC2, leading to activation of the cGAS-STING pathway, whereas in other tumor models it is production of 2′3′-cGAMP by tumor cells that is responsible for activation of host STING." (PMID 32508825, 2020). "Antigen-specific priming of T-cells can occur via a mechanism involving the transfer of tumour-cell-derived cGAMP into immune cells which then activates the cGAS-STING pathway." (PMID 33081170, 2020). "We found that the elevated immune scores are associated with the SLE, cGAS-STING cytosolic DNA-sensing and TGF-β signalling pathways, HR deficiency, neoantigen prediction and tumour heterogeneity." (PMID 33353943, 2020). "In doing so, the tumour-derived EV DNA was able to activate cGAS-STING and mediate an anti-tumour immune response." (PMID 32719324, 2020). "cGAS stimulation in tumor cells provide ligands for STING in myeloid cells to promote NK cell activation and antitumor response." (PMID 31601678, 2019). "As eluded to above, cGAS-STING dependent anti-tumor immunity is of crucial importance for the success of immunotherapy, such as anti PD-1 and anti-PD-L1 immunotherapy." (PMID 31658669, 2019). "Thirdly, cGAS-STING pathway elevates the sensitivity of tumor cell to immune killing activity of NK and CTL." (PMID 30935414, 2019). "cGAS knockout mice had lower numbers of tumor-specific CD4+ and CD8+ T-cells following immunotherapy when compared to wild-type ones." (PMID 31182960, 2019). "Tumor-derived DNA itself has also been shown to be a DAMP that stimulates the cGAS–STING pathway in DCs, inducing them to produce IFN-I." (PMID 31221199, 2019). "Tumor cell-derived DNAs can be detected by one of the major DNA sensors, cyclic GMP-AMP synthase (cGAS) (a cytosolic DNA sensor), which activates STING and then the TBK1 (the major kinase for IRF7 and IRF3 activation) pathway, thus inducing IFN-1 expression." (PMID 31049360, 2019). "Mice harboring a Rnaseh2bA174 mutation that show upregulation of interferon stimulated genes (ISG) in various tissues as a result of cGAS-STING activation are therefore also expected to be very sensitive to TNFα, similar to BRCA2 deficient tumor cells." (PMID 31658669, 2019). "In tumor microenvironment, cGAS-STING in DC plays an important role in the cross-presentation and priming of tumor-specific CD8+ T cell." (PMID 30935414, 2019). "Because the activation of the cGAS/STING pathway has been well documented as a tumor cell-intrinsic mechanism mediating the DNA damage-induced proinflammatory immune response, STING pathway activity was next evaluated in MDA-MB-436 cells." (PMID 30755715, 2019).
tumor (continued). "Although STING activation in tumor cells participates in anti-tumor immune response, active cGAS-STING pathway in host immune cells mainly contributes to tumor control." (PMID 30935414, 2019). "Such emerging evidence for cGAS-STING–mediated tumor promotion warrants further exploration of triggering other innate sensors for tumor therapy." (PMID 31601678, 2019). "Given that the cGAS-STING pathway plays an active role in eliminating tumor cells, one would assume that the alleviation of the pathway would provide a powerful means for cancer cells to duck immune surveillance, particularly when displaying a CIN phenotype." (PMID 31658669, 2019). "By infecting PD-L1low mouse tumor cell (2F8 cell) with cGAS-STING-encoding adenovirus, nearly all infected tumor cell expressed PD-L1 while 46% of tumor cells infected by control adenovirus expressed PD-L1." (PMID 30935414, 2019). "Actually, cGAS-STING pathway regulates anti-tumor immunity in a comprehensive manner from enhancing antigen presentation to increasing cytotoxicity." (PMID 30935414, 2019). "A growing body of evidence demonstrated the important role of cGAS-STING pathway in bridging anti-tumor innate immunity and adaptive immunity." (PMID 30935414, 2019). "Ruptured micronuclei are key signals to activate immune pathways that can control tumor progression via the cGAS-STING (STimulator of Interferon Gene) pathway." (PMID 30988276, 2019). "As shown for cell-intrinsic cGAS activation, cGAS cell-extrinsic activation also promotes the priming, expansion, and recruitment of tumor-specific T-cells through type I IFNs and their downstream pro-inflammatory molecules." (PMID 31658669, 2019). "Secondly, cGAS-STING agonist counteracts the decrease of major histocompatibility complex (MHC) molecules on tumor cell which is an important approach to escape immune surveillance." (PMID 30935414, 2019). "It is noteworthy that the cGAS-Sting pathway in tumor-infiltrating DCs can also sense tumor-derived genomic DNA, leading to IFN-β production and eventually CTL activation, highlighting the relevance of this antiviral pathway in cancer development and therapy." (PMID 31440242, 2019). "The tumor-derived DNA is recognized by cGAS, which produces cGAMP for STING activation and IFN-β production, facilitating the activation of antitumor CD8+ T cell responses in vivo." (PMID 31539404, 2019). "Combined, our results describe a mechanism by which autocrine TNFα signaling, induced by cGAS/STING signaling upon loss of the BRCA2 tumor-suppressor gene, limits tumor cell viability." (PMID 30626869, 2019). "Particularly, BATF3-tumor-infiltrating dendritic cells are stimulated by autocrine production of interferon β (IFN-β) upon detecting cell-derived dsDNA via the cGAS-STING pathway." (PMID 31179236, 2019). "In prostate cancer cells, MUS81 is responsible for cytoplasmic DNA that activates the cGAS-STING pathway responsible for interferon induction that can recruit myeloid cells to control tumour growth." (PMID 31500184, 2019). "Although cytosolic DNA is commonly found in tumor cells, cGAS-STING signaling is disrupted or silenced in many tumors, enabling cancer cells to evade immunosurveillance." (PMID 30080846, 2018). "Recent evidence from several groups have shown that the cGAS-STING pathway is responsible for detecting cytosolic tumor–derived DNA after RT-induced damage to the DNA." (PMID 30692991, 2018). "Uptake of tumor antigens by antigen presenting cells, e.g., dendritic cells, as well as sensing of cancer cell-derived cytoplasmic dsDNA by the cGAS/STING pathway are required for the priming of tumor-specific T cell responses." (PMID 30577587, 2018). "In a recent study, extreme high-dose radiation (20–30 Gy in 1 fraction) was shown to sabotage tumor immunogenicity by inducing DNA exonuclease Trex1 to block cGAS-STING pathway activation." (PMID 29556198, 2018).
tumor (continued). "Other DNA damaging agents such as anthracyclines have also been shown to signal through the cGAS-STING-IFN pathway to produce anti-tumor immune responses." (PMID 30692991, 2018). "Deng at al. demonstrated that the STING signaling axis is activated in DCs, and cGAS is essential for the sensing by the DC of irradiated-tumor cell derived dsDNA." (PMID 30619752, 2018). "The importance of the cGAS-STING pathway on the anti-tumor immune response stimulated by both radiation and anti-PD1/L1 has now been established." (PMID 30619752, 2018). "In the cGAS knockout mice there was a decrease in the number of tumor specific CD4 and CD8 T-cells relative to wild-type anti-PD-L1 treated." (PMID 30619752, 2018). "Then, tumor DNA escapes to the cytoplasm of DCs and activates the cGAS–STING pathway, inducing the production of type I IFN and the co-stimulatory molecule CD86, and activating a Th1 response." (PMID 29050360, 2017). "In line with the previous knowledge of radiation induced cellular stress and excessive DNA damage, this report has also indicated cGAS mediated sensing of irradiated-tumor cells by DCs." (PMID 29156566, 2017). "In both immunogenic and irradiation-induced tumour models, tumour-derived DNA was engulfed and recognised by the universal DNA sensor cGAS prior to STING activation." (PMID 28596706, 2017). "It has also been demonstrated that tumor-derived DNA is transferred to host DCs and induces IFNs production through cGAS-STING pathway for CD8+ T cell priming." (PMID 28216575, 2017). "DNA released from dying tumor cells can be sensed by the cytosolic enzyme cyclic GMP-AMP synthase (cGAS)." (PMID 28695111, 2017). "With the growing evidence and understanding of the role of cGAS/STING pathway in facilitating anti-tumor immunity, recent efforts are targeting to modulate this cGAS/STING pathway in context of cancer immune therapy." (PMID 29156566, 2017). "Pro-inflammatory signalling has the potential to cure tumours, and direct activation of the cGAS–STING pathway by small molecule STING agonists eliminates solid tumours in mice." (PMID 29142107, 2017). "The cytosolic DNA sensor cyclic Guanosine Monophosphate-Adenosine Monophosphate GMP-AMP (cGAMP) Synthase (cGAS) mediates the sensing of irradiate tumor cells in DCs." (PMID 27854240, 2016). "In vitro, IFN-β production and DC activation are triggered by tumor cell-derived DNA, via cyclic-GMP-AMP Synthase (cGAS), Stimulator of interferon genes (STING) and Interferon Regulatory Factor 3 (IRF3)." (PMID 27854240, 2016). "Tumor DNAs then activate the cGAS-STING pathway and type I IFN production in DCs, resulting in intense priming of T cells." (PMID 27696330, 2016). "Our data demonstrated that cGAS is selectively activated in ecDNA+ tumor cells." (PMID 41509453, 2026). "Interestingly, we show that these pancreatic adenocarcinoma cancer cells respond to cGAMP or cGAS expression in the tumor cells, demonstrating the efficacy of targeting the cGAS-STING pathway to rejuvenate antitumor response in these aggressive tumors." (PMID 41509453, 2026). "For instance, growing evidence suggests that DSF/Cu can induce ferroptosis and exert anti-tumor effects by modulating the tumor immune microenvironment through the activation of the cGAS-STING innate immunity pathway and the induction of immunogenic cell death 14-16." (PMID 41438581, 2026). "On the other hand, the reactive oxygen species (ROS) generated by the MnO2-mediated Fenton-like reaction, OXP, and mPTT also induce immunogenic cell death (ICD) to boost adaptive immunity, as well as activate the cGAS-STING pathway through tumor DNA damage to reinforce innate immunity." (PMID 41624521, 2026). "Therefore, restoration of the cGAS-STING pathway in ecDNA+ cancer cells inhibits tumorigenesis through both tumor-cell-intrinsic and -extrinsic mechanisms." (PMID 41509453, 2026). "Indeed, DNA sensing by cGAS is an important mechanism that activates the immune system, including anti-tumor immunity." (PMID 41509453, 2026).
tumor (continued). "However, the expression of cGAS and STING is often suppressed in tumor cells, and reduced expression is associated with poor prognosis and inferior response to immunotherapy." (PMID 40830678, 2026). "Our synthesis highlights the context-dependent nature of cGAS-STING signaling, with therapeutic outcomes shaped by STING pathway integrity, tumor mutational burden, cytosolic DNA load, and the immunologic composition of the tumor microenvironment." (PMID 42311657, 2026). "Subsequently, Mn2+ released from the TFM could be further released into the tumor microenvironment after cell death, which could be taken up by iDCs and upregulate the cGAS‐STING signaling pathway in iDCs." (PMID 41114460, 2026). "Therefore, more strategies of targeting cGAS-STING for reprogramming TAMs are warranted for enhancing anti-tumor immunotherapy." (PMID 40075527, 2025). "Another possibility is that tumor cells are known to secrete extracellular microvesicles (e.g., exosomes), which transport substances (e.g., tumor-derived dsDNA and the cGAS product cGAMP) from the tumor cells and present MHC antigens to the other surrounding cells." (PMID 40733503, 2025). "Consequently, anti-tumor strategies targeting the cGAS-STING pathway have to consider the balance of immune activation and the immune tolerance caused by chronic activation." (PMID 40052963, 2025). "Taking these results, CAFs can downregulate tumor cell-intrinsic cGAS–STING expression in CRC." (PMID 40451897, 2025). "Importantly, pharmacological inactivation of HMGCR significantly enhanced radiotherapy responsiveness in animal models, dependent on cGAS–STING signaling-mediated anti-tumor responses." (PMID 40355720, 2025). "Similarly, STING agonists activate the cGAS-STING signaling pathway, promoting the polarization of tumor-associated macrophages toward an M1-like phenotype, activating dendritic cells, and increasing the infiltration of CD8+ T and natural killer (NK) cells." (PMID 41331376, 2025). "Additionally, acute activation of cGAS-STING signaling induces remodeling of the tumor immune microenvironment to foster an anti-tumor state." (PMID 40052963, 2025). "When cGAS identifies the cytoplasmic double-stranded DNA fragment released by dead cells, tumor cells, or pathogens, cGAS catalyzes ATP and guanosine triphosphate to produce the second messenger 2’,3’-cyclic guanosine monophosphate, which binds and directly activates the STING protein." (PMID 40033359, 2025). "Similarly, immune checkpoint blockades (ICBs), oncolytic viruses, and tumor vaccines rely on cGAS-STING to amplify immune responses, particularly T-cell activation and dendritic cell (DC) cross-presentation." (PMID 40052963, 2025). "Mechanistically, BF839 induced tumor suppression was regulated by the cGAS-STING pathway." (PMID 40231233, 2025). "Notably, the discovery of tumor-derived DNA activating the cGAS-STING pathway has revealed new mechanisms of innate immune sensing within the tumor microenvironment." (PMID 40124373, 2025). "Tumor cells with increased expression of CGAS or STING1 showed enhanced interactions with T cells." (PMID 40735041, 2025). "In STING-intact mice, cGAS/STING activation in dendritic cells after direct sensing of irradiated tumor cells promotes cytotoxic T cell–driven antitumor responses through type 1 IFN signaling, and increased STING activation through exogenous cGAMP improves radiotherapy efficacy." (PMID 41392975, 2025). "Adenoviral vectors primarily induce anti-tumor responses via cGAS–STING pathway activation and the induction of immunogenic cell death (e.g., ONCOS-102, which achieved a 70% tumor shrinkage rate), as well as through dual co-stimulatory mechanisms (e.g., LOAd703)." (PMID 40977706, 2025). "Thus, targeting ferroptosis -cGAS-STING crosstalk offers a dual-pronged strategy for enhancing both tumor cell death and antitumor immunity, addressing the limitations of conventional therapies." (PMID 40846966, 2025).